RSPRY1 (ring finger and SPRY domain containing 1)
Synonyms: KIAA1972; SEMDFA
Tractability: Antibody: UniProt places it where antibodies can reach, with high confidence; UniProt predicts a signal peptide or a membrane-spanning region; its Gene Ontology location is reachable by antibodies, with medium confidence. PROTAC: ubiquitination databases record sites on it; its protein half-life has been measured.
Gene: Protein-coding gene on chromosome 16 (57,186,137 to 57,240,479, forward strand). Ensembl gene ENSG00000159579.
Subcellular location: Secreted
Gene Ontology:
Molecular function: ubiquitin-protein transferase activity
Cellular component: cytoplasm; extracellular region
Genetic constraint (gnomAD): Loss-of-function variants: 10 observed, 38.12 expected, observed/expected ratio (o/e) 0.26, 90% interval 0.16 to 0.44. The upper end of that interval is the gene's LOEUF score, 0.44, which puts it in group 1 of 6, group 1 being the genes least tolerant of losing a copy. Missense variants: 302 observed, 484.66 expected, observed/expected ratio (o/e) 0.62, 90% interval 0.57 to 0.69. Synonymous variants: 143 observed, 177.08 expected, observed/expected ratio (o/e) 0.81, 90% interval 0.7 to 0.93.
Homologues: Orthologues: chimpanzee RSPRY1 (100% identical), macaque RSPRY1 (99% identical), rabbit RSPRY1 (98% identical), dog RSPRY1 (97% identical), pig RSPRY1 (97% identical), rat Rspry1 (97% identical), guinea pig RSPRY1 (97% identical), mouse Rspry1 (97% identical), tropical clawed frog rspry1 (80% identical), zebrafish rspry1 (78% identical), Caenorhabditis elegans F16A11.1 (45% identical). Paralogues in human: RNF123 (18% identical).
Diseases named in the same sentence as RSPRY1 in open-access papers:
RSPRY1 is named in the same sentence as 6 diseases in open-access papers, as found by Europe PMC text mining. Sharing a sentence is not in itself a finding about the gene and the disease. The quoted sentences say what the papers report.
spondyloepimetaphyseal dysplasia (2 papers, 2024 to 2025). An osteochondrodysplasia that results in abnormalities of bone growth in the vertebral column, epiphysis, and metaphysis. "RSPRY1 gene mutations are associated with spondyloepimetaphyseal dysplasia (SEMD), a rare skeletal disorder characterized by severe epiphyseal and metaphyseal deformities." (PMID 39940902, 2025). "Biallelic variants in RSPRY1 have been found to result in spondyloepimetaphyseal dysplasia." (PMID 38562122, 2024). "Thus, our study provides further evidence to support the association of RSPRY1 variants with spondyloepimetaphyseal dysplasia." (PMID 38562122, 2024). "The present study is, to the best of our knowledge, the first to provide direct evidence that RSPRY1 deficiency leads to overactivation of the TGF-β signaling pathway, revealing a novel molecular mechanism underlying the pathogenesis of spondyloepimetaphyseal dysplasia (SEMD)." (PMID 39940902, 2025). "Spondyloepimetaphyseal dysplasia (SEMD), RSPRY1 related (OMIM #616723), also referred to as SEMD, Faden-Alkuraya type, is a rare autosomal recessive disorder." (PMID 38562122, 2024).
skeletal dysplasia (2 papers, 2024 to 2025). Any Mendelian diseases that affects growth and development of the skeleton. "Furthermore, the observed relationship between RSPRY1 deficiency and TGF-β signaling might provide a foundation for novel targeted therapeutic strategies for patients with SEMD and other related skeletal dysplasias." (PMID 39940902, 2025). "By highlighting the interplay between RSPRY1 and TGF-β1 signaling, the present study provides a foundation for developing targeted therapies for patients with SEMD and other related skeletal dysplasias." (PMID 39940902, 2025). "An improvement in our understanding of the molecular roles of RSPRY1 might yield novel therapeutic strategies that target TGF-β signaling in patients with SEMD and other skeletal dysplasias." (PMID 39940902, 2025).
RSPRY1 also shares sentences with these, for which no sentence is quoted: craniosynostosis (1 paper); Intellectual disability (1); sarcoidosis (1); scoliosis (1).